OR4C6 (olfactory receptor family 4 subfamily C member 6)
Description:
Odorant receptor.
Synonyms: OR11-138
Tractability: Antibody: UniProt places it where antibodies can reach, with medium confidence; UniProt predicts a signal peptide or a membrane-spanning region; its Gene Ontology location is reachable by antibodies, with medium confidence.
Gene: Protein-coding gene on chromosome 11 (55,662,201 to 55,666,195, forward strand). Ensembl gene ENSG00000181903.
Subcellular location: Cell membrane
Pathways (Reactome):
Sensory Perception: Expression and translocation of olfactory receptors
Gene Ontology:
Molecular function: olfactory receptor activity; G protein-coupled receptor activity
Biological process: detection of chemical stimulus involved in sensory perception of smell; G protein-coupled receptor signaling pathway
Cellular component: plasma membrane; membrane
Genetic constraint (gnomAD): Loss-of-function variants: 19 observed, 12.53 expected, observed/expected ratio (o/e) 1.52, 90% interval 1.04 to 1.92. The synonymous counts are far from expectation, so gnomAD's model fits this gene poorly and the ratio says little. Missense variants: 488 observed, 354.56 expected, observed/expected ratio (o/e) 1.38, 90% interval 1.28 to 1.48. Synonymous variants: 177 observed, 131.38 expected, observed/expected ratio (o/e) 1.35, 90% interval 1.19 to 1.53.
Homologues: Orthologues: chimpanzee OR4C6 (98% identical), dog OR4C6 (80% identical), dog OR4C59 (77% identical), mouse Or4c102 (76% identical), mouse Or4c123 (75% identical), rat Or4c130-ps1 (75% identical). Paralogues in human: OR4C5 (61% identical), OR4C12 (61% identical), OR4C13 (61% identical), OR4A15 (60% identical), OR4C46 (60% identical), OR4C15 (59% identical), OR4C3 (58% identical), OR4B1 (57% identical), OR4S2 (57% identical), OR4A47 (56% identical), OR4C45 (56% identical), OR4A5 (55% identical), and 116 more.
Diseases named in the same sentence as OR4C6 in open-access papers:
OR4C6 is named in the same sentence as 6 diseases in open-access papers, as found by Europe PMC text mining. Sharing a sentence is not in itself a finding about the gene and the disease. The quoted sentences say what the papers report.
Obesity (3 papers, 2015 to 2023). Accumulation of substantial excess body fat. "The block contains a copy number deletion involving OR4P4, OR4S2, and OR4C6 genes which is associated with early extreme obesity in previous studies using genotyping arrays and suggesting the link between olfactory dysfunction and obesity." (PMID 38110883, 2023). "In a genome-wide association study (GWAS), variants of three olfactory genes, OR4P4, OR4S2 and OR4C6, were found to be associated with obesity." (PMID 38248819, 2023). "Interestingly, a common copy number variant region was identified on chromosome 11q11 associated with obesity and exclusively covering three OR genes, OR4p4, OR4S2 and OR4C6." (PMID 25943692, 2015).
breast carcinoma (2 papers, 2017). "We have replicated CNVs (n = 5) from the familial breast cancer study, including CNVs in genes ANKS1B19, OR4C11, OR4P4, UGT2B17, OR4C6, OR4S215." (PMID 29116104, 2017).
pancreatic carcinoma (2 papers, 2018 to 2022). "As ZRANB2 is upregulated in types of ovarian carcinoma and acts on the alternative splicing of genes implicated in tumor development, we suggest a role for OR4C6 in the development of pancreatic cancer." (PMID 29497600, 2018). "Olfactory receptor family 4 subfamily C member 6 (OR4C6) was reported as a possible biomarker for pancreatic carcinoma." (PMID 35592316, 2022). "Analysis of the expression pattern of ORs in 20 pancreas carcinoma tissues and cell lines revealed increased expression of OR4C6." (PMID 29497600, 2018). "In pancreatic carcinoma tissues, OR4C6 was considerably more highly expressed in comparison to the respective healthy tissues." (PMID 29497600, 2018). "The highest expression was demonstrated for OR4C6, which had a moderate expression in several pancreatic carcinoma tissues, but not in healthy pancreas tissue." (PMID 29497600, 2018).
OR4C6 also shares sentences with these, for which no sentence is quoted: ovarian carcinoma (1 paper); pancreas carcinoma (1); tumor (1).